DDI2 (DDI proteasomal shuttling factor 2)
Description:
Aspartic protease that mediates the cleavage of NFE2L1/NRF1 at 'Leu-104', thereby promoting release of NFE2L1/NRF1 from the endoplasmic reticulum membrane. Ubiquitination of NFE2L1/NRF1 is a prerequisite for cleavage, suggesting that DDI2 specifically recognizes and binds ubiquitinated NFE2L1/NRF1. Seems to act as a proteasomal shuttle which links the proteasome and replication fork proteins like RTF2 (Probable). Required, with DDI1, for cellular survival following replication stress. Together or redundantly with DDI1, removes RTF2 from stalled forks to allow cell cycle progression after replication stress and maintains genome integrity.
Synonyms: MGC14844; RSC1A1
Tractability: PROTAC: ubiquitination databases record sites on it; its protein half-life has been measured.
Gene: Protein-coding gene on chromosome 1 (15,617,458 to 15,669,044, forward strand). Ensembl gene ENSG00000197312.
Subcellular location: Cytoplasm, cytosol; Chromosome
Subcellular location (Human Protein Atlas): Cytosol; Nucleoplasm
Gene Ontology:
Molecular function: aspartic-type endopeptidase activity; identical protein binding; protein binding; ubiquitin binding
Biological process: cellular response to hydroxyurea; proteasomal protein catabolic process; protein processing; regulation of DNA stability; regulation of protein stability; proteolysis
Cellular component: chromosome; cytosol; nucleoplasm; cytoplasm
Genetic constraint (gnomAD): Loss-of-function variants: 5 observed, 47.06 expected, observed/expected ratio (o/e) 0.11, 90% interval 0.055 to 0.22. The upper end of that interval is the gene's LOEUF score, 0.22, which puts it in group 1 of 6, group 1 being the genes least tolerant of losing a copy. Missense variants: 285 observed, 519.17 expected, observed/expected ratio (o/e) 0.55, 90% interval 0.5 to 0.61. Synonymous variants: 205 observed, 191.52 expected, observed/expected ratio (o/e) 1.07, 90% interval 0.95 to 1.2.
Homologues: Orthologues: chimpanzee DDI2 (100% identical), guinea pig DDI2 (85% identical), tropical clawed frog ddi2 (85% identical), zebrafish ddi2 (79% identical), Drosophila melanogaster rngo (48% identical), Caenorhabditis elegans ddi-1 (29% identical). Paralogues in human: DDI1 (71% identical), UBAC2 (15% identical), NRIP3 (13% identical), NRIP2 (13% identical).
Diseases named in the same sentence as DDI2 in open-access papers:
DDI2 is named in the same sentence as 14 diseases in open-access papers, as found by Europe PMC text mining. Sharing a sentence is not in itself a finding about the gene and the disease. The quoted sentences say what the papers report.
multiple myeloma (6 papers, 2016 to 2024). "While this study was underway, two other laboratories found that knockout of DDI2 reduced recovery of proteasome activity in multiple myeloma and NIH-3T3 cells pulse-treated with PIs by ~30%." (PMID 38619391, 2024). "The DDI2-dependent NRF1 pathway has been mostly proposed to contribute to susceptibility and resistance to treatments with proteasome inhibitors in multiple myeloma." (PMID 37720101, 2023). "Previous reports demonstrated a beneficial effect of targeting DDI2 using nelfinavir in cancer treatments including in Multiple Myeloma." (PMID 36248746, 2022). "Recognizing the potential importance of DDI2 in the context of proteasome inhibitor therapy in cancer treatment, we also investigated the effect of DDI2 KO in the myeloma cell line U266B, which was shown to be sensitive to the first generation of proteasome inhibitors." (PMID 32521225, 2020). "Moreover, also in multiple myeloma cells, DDI2 KO has the effect of perturbing the processing of ubiquitylated proteins (compare lane 1 to lane 5)." (PMID 32521225, 2020). "Finally, our results, including those on multiple myeloma cells lacking DDI2, support the idea that inhibition of DDI2 protease might have clinical benefit in cancer therapy, alone or in conjunction with proteasome inhibition." (PMID 32521225, 2020).
colorectal cancer (4 papers, 2020 to 2022). A primary or metastatic malignant neoplasm that affects the colon or rectum. "The functions of DDI2 in cancer biology have only been reported in colorectal cancer and thyroid cancer." (PMID 35783157, 2022). "DDI2 was recently identified to act as an oncogene to promote the tumorigenesis of colorectal cancer." (PMID 31947743, 2020). "In colorectal cancer, miR-3607 was also found to suppress tumor cell proliferation, migration and invasion through targeting DDI2." (PMID 32404179, 2020).
cervical cancer (3 papers, 2022 to 2023). A primary or metastatic malignant neoplasm involving the cervix. "Downregulation of this particular lncRNA was associated with overexpression of miR-205–3p and downregulation of DDI2 in cervical cancers." (PMID 37019990, 2023). "We confirm that FAM13A-AS1 upregulates DNA-damage inducible 1 homolog 2 (DDI2) expression through miRNA-205-3p to suppress cervical cancer progression, which implicates FAM13A-AS1 as a potential biomarker for cervical cancer treatments." (PMID 35783157, 2022). "In the present study, we indicated that the expression of DDI2 in cervical cancer tissue was significantly lower than in normal tissue." (PMID 35783157, 2022). "RT-qPCR also confirmed that the expression of DDI2 in cervical cancer was lower than in normal tissue." (PMID 35783157, 2022). "In conclusion, FAM13A-AS inhibited the progression of cervical cancer by targeting the miR-205-3p/DDI2 axis." (PMID 35783157, 2022). "In conclusion, FAM13A-AS1 inhibits the progression of cervical cancer by targeting the miRNA-205-3p/DDI2 axis, suggesting that FAM13A-AS1 might be a potential target for cancer cell treatment." (PMID 35783157, 2022). "In cervical cancer cell lines, overexpression of FAM13A-AS1 increased the DDI2 expression level, and the miR-205-3p inhibitor also increased the expression of DDI2, while miR-205-3p mimic reversed these effects." (PMID 35783157, 2022). "In cervical cancer, lncRNA FAM13A-AS1/miRNA-205-3p/DDI2 axis and lncRNA PTENP1/miR-106b/PTEN axis can jointly promote apoptosis and inhibit the progression of cervical cancer, while lncRNA HOXD-AS1 plays an anti-apoptosis role to promote the progression of cervical cancer." (PMID 37313458, 2023).
triple-negative breast carcinoma (3 papers, 2020 to 2024). An invasive breast carcinoma which is negative for expression of estrogen receptor (ER), progesterone receptor (PR), and human epidermal growth factor receptor 2 (HER2). "Next, we knocked down DDI2 by two different highly efficient siRNAs in two PI-sensitive triple-negative breast cancer cell lines, SUM149 and MDA-MB-231." (PMID 38619391, 2024). "Alterations of DDI2 functions were found to potentiate the cytotoxicity of PI in a triple-negative breast cancer model, indicating that this protease could interfere with clinical responses to proteasome inhibition." (PMID 35589686, 2022). "Furthermore, using a triple-negative breast cancer cell line MDA-MB-231, we investigated the therapeutic utility of attenuating DDI2 function." (PMID 31947743, 2020).
thyroid cancer (2 papers, 2022). "The molecular role of DDI2 in thyroid cancer is almost unknown." (PMID 36232810, 2022).
acute myeloid leukemia (1 paper, 2020). Acute myeloid leukemia (AML) is a group of neoplasms arising from precursor cells committed to the myeloid cell-line differentiation. "Indeed, Nrf1, DDI2, and NGLY1 exhibit a correlated essentiality for cell survival in several acute myeloid leukemia (AML) cell lines." (PMID 32456207, 2020).
anaplastic thyroid cancer (1 paper, 2022). "This experimental approach allowed us to identify DDI2 as a gene specifically controlled by the m6A modification in anaplastic thyroid cancer cell lines." (PMID 36232810, 2022).
breast adenocarcinoma (1 paper, 2020). "Recently, it was shown that DDI2-deficient or protease-dead DDI2 mutant MDA-MB231 human breast adenocarcinoma cells are more sensitive to carfilzomib-induced apoptosis, suggesting that DDI2 is significant to the bounce-back response." (PMID 32456207, 2020).
glioma (1 paper, 2021). A benign or malignant brain and spinal cord tumor that arises from glial cells (astrocytes, oligodendrocytes, ependymal cells). "Therefore, the increase of circ_0000020 expression in glioma tissues and cell lines may be related to the expression of oncogene DDI2, which remains to be validated in the future." (PMID 33509213, 2021).
thyroid tumor (1 paper, 2022). A benign or malignant neoplasm affecting the thyroid gland. "Both of these hypotheses could support a relevant role of DDI2 both as a biomarker and as one of the players involved in the aggressiveness of ATCs, compared with healthy tissue or more differentiated thyroid tumors." (PMID 36232810, 2022).
cancer (14 papers, 2012 to 2025). A tumor composed of atypical neoplastic, often pleomorphic cells that invade other tissues. "Nrf1, NGLY1, and DDI2 are co-essential in some cancer cell lines, suggesting that Nrf1-dependent regulation of the proteasome promotes proliferation of cancer cells." (PMID 38991033, 2024). "Given the widespread use of proteasome inhibitors in cancer therapy, this aspect of DDI2 and NRF1 function has obvious clinical implications." (PMID 32521225, 2020). "Our data using NFV for inhibiting DDI2 indicate that this could be a potential add-on treatment for targeting ferroptosis in cancer therapy, similar to what has been rationalized for proteasome inhibitors." (PMID 39384955, 2025). "Further, inhibitors of NGLY1 or DDI2 may synergize with proteasome inhibitor drugs for treatment of some cancers." (PMID 38991033, 2024). "Thus, the additive effects of nelfinavir and proteasome inhibitors in mediating the killing of cancer cells likely involve several mechanisms, which are dependent on Ddi2." (PMID 35358511, 2022). "We reasoned that DDI2 depletion could sensitize these cancer cells to CFZ-induced apoptosis via inhibition of the NRF1-mediated bounce-back response." (PMID 31947743, 2020). "However, for this to be a viable strategy, demonstration is critical of the requirement of DDI2 and Nrf1 for this compensatory mechanism in actual human-cancer-patient samples." (PMID 32033280, 2020). "In such a scenario, targeting Ddi2 along with the proteasome may prevent bounce back and enable devising of a successful strategy for treating cancer." (PMID 30186740, 2018). "A more recent study suggests that DDI2 plays a pro-tumoral role by activating NRF1 and ultimately increasing the ability of cancer cells to degrade ubiquitinated proteins in a proteosome-dependent manner." (PMID 36232810, 2022). "KIT, CDH1, LSM7, C21orf4, DDI2 mRNA expression levels were significantly different between benign and malignant tumors, p(KIT) < 0.0001; p(CDH1) = 0.004; p(LSM7) = 0.03; p(C21orf4) = 0.01; p(DDI2) = 0.0001." (PMID 22958914, 2012). "However, the trend was consistent and suggested that while NFV function by decreasing DDI2 proteolytic activity, additional targets contribute to NFV-mediated toxicity in cancer." (PMID 35589686, 2022). "This suggests that the HIVp inhibitors used in HIV treatment could inhibit DDI2-mediated activation of NRF3, abrogating aberrant 20S proteasome activity in cancer cells." (PMID 32123008, 2020). "To date, it has not been demonstrated if impairing DDI2 can sensitize cancer cells to proteasome inhibitor-induced apoptosis." (PMID 31947743, 2020).
tumor (4 papers, 2020 to 2022). "We further found that the expression of DDI2 was lower in the tumor group compared with the normal group of the targets with a high binding score." (PMID 35783157, 2022). "Immunohistochemistry was performed to detect the expression of DDI2 and the tumor cell proliferation factor Ki67." (PMID 35783157, 2022). "The expression of FAM13A-AS1, miR-205-3p, and DDI2 in tumor tissues was evaluated by RT-qPCR." (PMID 35783157, 2022). "Under acidic tumor microenvironment (TME) and 808 nm laser irradiation, BTZ is released and ROS is generated by Ce6 to destroy the “bounce‐back” response pathway proteins, such as DDI2 and p97, which can effectively inhibit proteasomes and increase apoptosis." (PMID 35068071, 2022). "Though it was not demonstrated if the oncogenic property is related to DDI2′s protease activity or an alternative, such as serving as an ubiquitin receptor protein, it is possible that a DDI2 protease inhibitor may have anti-tumor activity independent of the NRF1-mediated bounce-back response." (PMID 31947743, 2020).
DDI2 also shares sentences with these, for which no sentence is quoted: breast carcinoma (1 paper); myopia (1).